CTLA4 (cytotoxic T-lymphocyte associated protein 4)
Diseases named in the same sentence as CTLA4 in open-access papers (continued):
Sharing a sentence is not in itself a finding about the gene and the disease.
cancer (continued). "The discovery that CTLA-4 can impede T cell activation provided the basis for the notion that interrupting its function might allow T cells to mount a therapeutic attack on cancer." (PMID 37441075, 2023). "ICIs, including cytotoxic T lymphocyte protein 4 (CTLA-4), programmed cell death 1 (PD-1), and programmed cell death ligand 1 (PD-L1), mainly target proteins that negatively regulate T cell-meditated host immune response to cancer, thus enabling immune activation and antitumor response." (PMID 36950013, 2023). "The studies conducted by our research team on the interaction between CTLA-4 and CD86 in the course of CLL in the context of EBV reactivation, as well as the currently presented studies, show how important this pathway is in inhibiting the anti-cancer response." (PMID 37835480, 2023). "Recently, immune checkpoint‐modulating agents (represented by anti‐CTLA4 and anti‐PD antibodies), CAR‐T cells, and neoantigen vaccines have been seen to be successful in enhancing the antitumor effect in numerous types of cancer, bringing a paradigm shift to cancer treatment." (PMID 36129020, 2023). "CD86, a ligand of T cell surface receptor CTLA4, was not expressed on cancer cells." (PMID 37762490, 2023). "Monoclonal antibodies targeting inhibitory immune checkpoints, including CTLA-4, PD-1, Programmed Cell Death 1 Ligand 1 (PD-L1), and Lymphocyte-Activation Gene 3 (LAG-3) capable of interfering with negative signals provided by these molecules have revolutionized cancer treatment." (PMID 37296876, 2023). "CTLA-4 is expressed by T cells and binds to its ligands CD80 or CD86, which are present on professional antigen-presenting cells, while PD-1 is expressed by T cells and many other immune cell types, and its ligand PD-L1 is present on several types of immune cells but also somatic cells and cancer." (PMID 37342323, 2023). "Indeed, it showed that CTLA-4 mediated negative signals into cancer cells, compared with the ones currently observed in T cells." (PMID 37568193, 2023). "However, not all cancer patients benefit from single or combination therapy with anti-CTLA-4 and anti-PD-1/PD-L1 monoclonal antibodies." (PMID 37670328, 2023). "Additionally, several other immunologically relevant pathways were modulated by SS (PKCθ, OX40, CTLA4, PDL1/PD1, Nur77, DC maturation) as well as pathways relevant to CSC maintenance (Molecular Mechanisms of Cancer, Hypoxia, PI3K/AKT, Wnt, ERK5), all of which cross-talk with Notch." (PMID 37901240, 2023). "For instance, evidence has shown that CTLA4 inhibitors combined with PD-1 or PD-L1 agents can bring about higher incidence and severity of irAEs, such as the combination of ipilimumab and nivolumab, irrespective of the primary cancer treated." (PMID 36765782, 2023). "In addition, a study reported the development of MG in 12 of 9,869 cancer patients on nivolumab (PD-1 inhibitors) and none of 408 patients on ipilimumab (CTLA4 inhibitor) during the same period." (PMID 36936960, 2023). "Because CTLA-4 and PD-1/PD-L1 are the main negative immunomodulatory receptors that weaken T-cell activation and the immune response, tumors can use this mechanism to prevent the immune system from discovering and killing cancer cells." (PMID 36593951, 2023). "Expressed by activated T cells and transmits an inhibitory signal to T cells;CTLA4 expression has been found in many cancers, including non-small-cell lung cancer (NSCLC) tissues and cells; its function in cancer cells is unknown." (PMID 36675020, 2023). "Immune checkpoint inhibitors (anti-PD-1/PD-L1 and anti-CTLA-4 mAbs), dendritic cell (DC)-based vaccines, cytokine-induced killer (CIK) cells, cytotoxic T lymphocytes (CTLs) and CAR-engineered T cells are approved as monotherapies or combination treatments for different types of cancer." (PMID 35879685, 2022).
cancer (continued). "Although immune checkpoint blockers (ICBs) such as anti-CTLA-4 antibody ipilimumab, anti-PD-1 antibodies nivolumab and pembrolizumab, and anti-PD-L1 antibody atezolizumab have been evaluated in the treatment of many different cancers, ICB therapy works only on certain types of cancers." (PMID 36376874, 2022). "In addition, the development of irAEs was associated with the beneficial effects of treatment on survival in patients with cancer treated with PD-1 inhibitors but not in those treated with CTLA-4 inhibitors." (PMID 36052257, 2022). "However, another study did not report intratumoral depletion of Treg cells in cancer patients treated with anti-CTLA-4 therapies." (PMID 36713389, 2022). "This may indicate that the non-Treg depleting activity of anti-CTLA-4 therapy could benefit cancer patients." (PMID 35237846, 2022). "In addition to PD-1/PD-L1 and CTLA-4 as the most important immune checkpoints, emerging evidence indicates LAG3, TIM-3, TIGIT, VISTA, and other immune checkpoints are the representative ones in malignant tumor." (PMID 35991556, 2022). "In addition, the overexpression of immune checkpoints and the loss of anti-immune checkpoint molecules are regarded as significant mechanisms resulting in immune escape of tumours, thus cancer checkpoint inhibitors, such as anti-PD1, anti-CTLA4, and anti-PDL1 are widely used in cancer treatments." (PMID 35838271, 2022). "However, no relevant studies examining the effect of conventional cancer therapies on the immunosuppressive role of CTLA-4 have been published." (PMID 35281086, 2022). "Genetic alteration of CTLA-4 in humans has been associated with GC development;419 however, CTLA-4 may not be a good target in treating cancer according to the current knowledge." (PMID 36209270, 2022). "We further explored the correlation between the expression of LIPT1 and eight immune checkpoints (PD-L1, CTLA4, HAVCR2, LAG3, PDCD1, PDCD1LG2, SIGLEC15, and TIGIT), and found that LIPT1 levels were correlated with the expressions of these immune checkpoints, especially PD-L1, in most cancer types." (PMID 35837286, 2022). "In addition to PD-1, another combination therapy with EGFRvIII-directed CAR T cell engineered to express anti-CTLA-4 and PD-1 antibodies, is in the second phase I/II clinical trial (NCT03182816), showing improved persistence and activity of T cells in its cancer killing capacity." (PMID 36353540, 2022). "So far, the combination of NIR-PIT with immune checkpoint inhibitors such as anti-PD-1 and anti-CTLA-4 mAbs, or with activation cytokines such as IL-15 have been tested and shown effective in augmenting the efficacy of cancer-cell targeted PIT by enhancing the anti-cancer immune activation." (PMID 36185287, 2022). "Therefore, regulating CTLA-4 acetylation modification in combination with an anti-CTLA-4 strategy might relieve T cell deactivation and produce a curative effect in cancer immunotherapy." (PMID 35585975, 2022). "Over the last decade, the introduction of T cell targeted immunomodulators blocking immune checkpoints CTLA-4 and PD1 or PDL1 has been unprecedented, with immune checkpoint inhibitors (ICI) being used as single agents or in combination with chemotherapies in about 50 cancer types." (PMID 35428302, 2022). "Thus, we are going to construct the fourth-generation CAR-T cells to secrete a PD-1- or/and CTLA-4-blocking scFv together with IL-7 and CCL19, which may maximize the efficiency of CAR-T therapy for malignant solid tumors." (PMID 36479116, 2022).
cancer (continued). "Currently, in the immunotherapy of cancer, the most common targets within negative immune checkpoints are PD-1 (programmed death 1), its ligand PD-L1 (programmed death ligand 1), and CTLA-4 (cytotoxic T lymphocyte antigen 4) molecule when combination therapy is considered." (PMID 35328510, 2022). "Clinical data derived from PWH on ART with or without malignancy indicate a modest effect of reversing HIV latency with the clearest effects to date seen in individuals receiving combination blockade that included anti-CTLA-4." (PMID 35123267, 2022). "Targeting these IRs has been validated as a promising therapeutic strategy against cancer, and potentially chronic infection, as illustrated by clinical success achieved with immune checkpoint blockade (ICB) using monoclonal antibodies (mAbs) against PD-1 and CTLA-4 in metastatic melanoma." (PMID 35874734, 2022). "Moreover, immune checkpoint genes (such as PD1/PD-L1, LAG-3, CTLA-4, and HAVCR2) have been certified to participate in the immune suppression process of multiple tumors and targeted inhibitors have also been applied to specific immunotherapy for cancers." (PMID 35754848, 2022). "Consistent with previous reports, patients with cancer showed immune exhaustion phenotype as indicated by increased cell-surface expression of PD-1, TIGIT, and Tim-3 but reduced CD28 expression on CD8+ T cells and Vγ9Vδ2+ T cells, while cell surface CTLA-4 was barely detectable." (PMID 35318258, 2022). "Currently, several therapeutic approaches such as PD-1/PD-L1 and CTLA-4 inhibitors have been appraised in attempts to combat aggressive cancers such as PDACs and MCCs, but have failed to produce durable responses in PDACs and led to treatment resistance in some MCCs." (PMID 36498833, 2022). "The 2018 Nobel Prize in Physiology or Medicine awarded to Professors Tasuko Honjo (for his work on PD-1) and James Allison (for his work on CTLA-4) was undeniable proof of the enormous contribution of the discovery of these two negative control points to modern cancer treatment." (PMID 35328510, 2022). "Whether TET2 participates in immune checkpoint suppression mediated by the CTLA-4 or PD-1 pathway, whether and how TET2 acts on CD8+ cytotoxic T lymphocytes, and coordination of PD-L1/CTLA-4 to regulate the anti-cancer CD8+ T-cell response remain to be studied further." (PMID 35223782, 2022). "Furthermore, Tregs in TME have been shown to express upregulated levels of immune checkpoint molecules such as CTLA-4, PD-1, TIM-3 that can further inhibit the anti-cancer immune response by inhibiting effector T cells and influencing the function of antigen-presenting cells (APCs)." (PMID 35714487, 2022). "However, reactivation of T cells through ICBs such as anti-PD-1 or anti-CTLA4 antibodies alone cannot antagonize all immune resistance mechanisms, and a significant proportion of patients with cancer do not respond to ICB treatment." (PMID 36230744, 2022). "The proportion of responder for immunotherapy in the high VCAN group was significantly lower than the low VCAN group, and the AUC value of VCAN expression was higher than that of PD-L1, PD1 and CTLA4 expression, which suggested that VCAN might predict immunotherapy efficacy in other cancers." (PMID 36203562, 2022). "However, according to the clinical database, there is no pan-cancer analysis available for PD-1, PD-L1, and CTLA-4." (PMID 36147250, 2022). "However, most cancer patients do not respond to treatment with PD-1/PD-L1 inhibitors or CTLA-4 inhibitors." (PMID 35911673, 2022). "The last two mechanisms explain how CTLA-4 could prevent anti-cancer immune reactions without the need for Treg cells." (PMID 33809974, 2021). "However, a recent contradictory result showed that FOXP3+ Tregs were not affected in cancer patients treated with anti‐CTLA4 therapies." (PMID 34185431, 2021).
cancer (continued). "However, in cancer, the CD28 homologue CTLA-4 is translocated from intracellular storage to the plasma membrane of T cells, competitively binds to B7 ligands on antigen presenting cells (APCs) with higher affinity, thereby preventing CD28-mediated T cell activation." (PMID 35047074, 2021). "Additionally, monotherapies of PD-1 inhibitors are associated with higher overall survival rates than monotherapies of other immune checkpoint inhibitors such as ipilimumab (anti-CTLA-4 monoclonal antibody) and BRAF/MEK inhibitors; also, they can be used for the treatment of a variety of cancers." (PMID 33681388, 2021). "However, currently, the immune checkpoint blockades such as PD-1, PD-L1, and CTLA-4 do not exhibit an overwhelming situation for conquering cancers." (PMID 34381812, 2021). "Therefore, in this study, we attempted to convert the negative CTLA4-CD86/CD86 signal by generating a novel CTLA4 signaling pathway in T cells to disrupt the interaction of immune checkpoint inhibitors CTLA4 and CD80/CD86 to effectively treat CD80/CD86-expressing cancer." (PMID 33868277, 2021). "In 2018, two pioneer immunotherapy innovators, Tasuku Honjo and James P. Allison, were awarded the Nobel Prize for their landmark cancer immunotherapy work regarding “cancer therapy by inhibition of negative immune regulation” –CTLA4 and PD-1 immune checkpoints." (PMID 34158025, 2021). "As such, Rab11 influences the amount of CTLA‐4 at the plasma membrane and so this specific step may be of interest in potential therapies that hope to more subtly regulate CTLA‐4 function, to treat autoimmune conditions or cancer." (PMID 33960403, 2021). "However, cancer cells develop innate or adaptive immune resistance and progress while being treated with anti-VEGF therapy or immune checkpoints inhibitors (ICIs), such as an anti-PD-1 antibody or an anti-CTLA4 antibody." (PMID 33416945, 2021). "Although PD-1, CTLA-4, LAG-3, and TIM-3 are equally important in CD8+ T cells, this may highlight the synergistic effect of Ogr1 and existing immunosuppressive checkpoint inhibitors in the treatment of advanced cancers." (PMID 34158625, 2021). "Furthermore, PD-1 and CTLA4 repression in T cells represent major obstacles to the efficacy of CAR-T treatment, and PD-1 and CTLA4 blockade by monoclonal antibodies have been intensively explored in cancer treatment." (PMID 33070170, 2021). "However, tumor-targeted radiotherapy, which may generate in situ vaccination following induction of immunogenic cell death of cancer cells, shows a broader TCR repertoire and increases antitumor efficacy to an anti-CTLA-4 antibody." (PMID 33909103, 2021). "Therefore, it is not surprising that CTLA4 is characterized by PWAS as a protective gene, with gene damage being associated with reduced cancer prevalence in the UKB cohort." (PMID 34290314, 2021). "The CTLA-4 co-inhibitory receptor is constitutively expressed on T cells and competes with CD28 co-stimulatory receptor for binding to their cognate ligands CD80 (B7.1) and CD86 (B7.2) on cancer cells, for which it has a greater affinity, thereby effectively inhibiting CTL activation." (PMID 33808294, 2021). "In addition, ICB-related pathways, including cancer immunotherapy by PD-L blockade (NES = 2.41, FDR < 0.001), the CTLA-4 pathway (NES = 2.55, FDR < 0.001) and CD28 family costimulation (NES = 2.45, FDR < 0.001), were related to the upregulated genes in this subtype." (PMID 34465315, 2021). "These two elegant study together suggested the specific immune microenvironment of LM and ICI based combination therapy (e.g. plus CTLA-4 inhibitor, EZH2 inhibitors, radiotherapy, etc.)could rescue systemic antitumor immunity and improve the prognosis of cancer patients with LM." (PMID 34248939, 2021).
cancer (continued). "In the present investigation, in which we used a different model of the transplantable cancer and the ultra-low dose WBIs rather than high-dose localized radiation, addition of the blockers of CTLA-4, PD-1, and/or HSP90 hardly improved the well-pronounced anti-neoplastic effect of WBI." (PMID 34208396, 2021). "This review will describe the mechanisms of CTLA-4 immune checkpoint inhibition, the role of Treg cells in tumorigenesis, and how anti-CTLA-4 antibodies can provoke an alteration in the expression of CTLA-4 on Treg cells while exerting anti-cancer therapeutic activity." (PMID 33809974, 2021). "However, a large proportion of cancer patients failed to respond to the treatment of blocking antibodies against the PD-1, PD-L1 or CTLA-4 immune checkpoint axis." (PMID 33721026, 2021). "However, ICIs for CTLA4 blockade are not commercially available for canine cancer patients due to the lack of species-specific mAbs." (PMID 34675296, 2021). "The discovery of immune checkpoint pathways such as the CTLA-4 and PD-1 axes, and their subsequent blockade by inhibiting antibodies (including, but not restricted to, anti-CTLA-4, anti-PD-1 and anti-PD-L1) has revolutionized the field of immunotherapy for cancer." (PMID 34367166, 2021). "However, although the ICB of negative co-receptors on T cells, such as CTLA-4 and PD-1, is an increasingly popular approach in cancer treatment, many patients do not respond to these treatments or develop resistance to them." (PMID 32526891, 2020). "Indeed, anti-CTLA-4, anti-PD1, and anti-PDL-1 antibodies are now used as therapies for cancers." (PMID 32489646, 2020). "Partial blockade of CTLA-4 shows therapeutic potential as it increases the antineoplastic effect of non-selective cytotoxic substances contributing to tumor regression in experimental cancer models, whereas non-immunogenic tumors are resistant." (PMID 32555170, 2020). "Notably, as opposed to standard chemotherapy, a non-negligible percentage of BRAF-mutated cancer patients are benefitting from BRAF and/or MEK inhibitors and/or immunotherapy (anti-CTLA-4, -PD-1, -PD-L1) in terms of OS and tolerable toxicity." (PMID 33260892, 2020). "Unlike CTLA-4, activation of the PD-1 signaling pathway mainly occurs in the effector phase of the adaptive immune suppression cascade, and it blocks the capacity of cytotoxic T cell to eliminate cancer cells." (PMID 31968651, 2020). "With their Nobel Prize winning research, Allison and Honjo argued for a new approach to cancer therapy with very promising outcomes using the inhibition of negative immune regulation by inhibiting the CTLA4 and PD1 immune checkpoints that allow T cells to eradicate cancer cells." (PMID 32906638, 2020). "Thus, agents that target alternative co-inhibitory pathways, such as anti-CTLA-4 antibody and anti-LAG3 antibody, may be effective in cancers with a T3 TIME." (PMID 32245497, 2020). "The solution to this issue might lie in their combination with immune checkpoint blockade (ICB) therapy, which has gained prominence in recent years and demonstrated immense potential for cancer therapy, with anti-PD-1, anti-CTLA4, anti-CD47 now widely in use as anti-cancer agents." (PMID 32774773, 2020). "Regardless of the mechanism(s) by which CTLA‐4 regulates DC function, these data highlight this inhibitory receptor as a relevant innate checkpoint in DC that can be targeted to enhance the immunostimulatory activity of these cells in the context of cancer." (PMID 32508018, 2020). "However, using anti-PD1 monotherapy or the combination of anti-PD1 and anti-CTLA4 is still limited to a minority of cancer patients, and a vast majority of patients do not derive clinical benefit due to primary resistance." (PMID 32850393, 2020).